IDH1 (isocitrate dehydrogenase (NADP(+)) 1)
Diseases named in the same sentence as IDH1 in open-access papers (continued):
Sharing a sentence is not in itself a finding about the gene and the disease.
glioma (continued). "As expected, across all gliomas, the prevalence of IDH1/2-mutant gliomas decreased as patients became older, with only 75 out of 966 patients ≥65 years old having an IDH1/2-mutant astrocytoma or oligodendroglioma." (PMID 39164213, 2025). "Mutation in one of the two isocitrate dehydrogenases (IDH1 and IDH2) is very common in gliomas (70–80%)." (PMID 40983311, 2025). "Temporal lobe (80.3%) and thalamic/basal ganglia (90.4%) gliomas predominantly belonged to the IDH1/2-wild-type glioma subtype." (PMID 41377022, 2025). "Piezo1 expression was significantly higher in the IDH1 wild-type group of gliomas than in the IDH1 mutant group and was elevated in the 1p/19q-non-co-deletion group." (PMID 40061015, 2025). "The difference in molecular expression leads to survival differences at the individual level; for example, patients with glioblastoma carrying wild-type IDH1/2 have a shorter median survival period compared to other gliomas." (PMID 41201287, 2025). "IDH1 and also IDH2 gene mutations have been identified in several types of cancers, such as gliomas, conventional central and periosteal malignant cartilaginous tumours, cytogenetically normal acute myeloid leukaemia, and cholangiocarcinoma." (PMID 40182999, 2025). "The results reveal significant interactions between PD-L1 and IDH1 (R132H) in the tumor microenvironment, shedding light on the immune landscape of gliomas." (PMID 39906459, 2025). "The application of machine learning in glioma classification has gained significant attention, particularly in predicting IDH1 genotype, a key molecular marker influencing treatment strategies." (PMID 40299088, 2025). "In contrast, IDH1 wild-type low-grade gliomas and glioblastomas exhibited lower EIF3J-AS1 expression." (PMID 41390674, 2025). "The mutation of IDH1 suppresses STAT1, a regulator of CXCL10, leading to reduced CD8+ T cell accumulation in gliomas." (PMID 40075726, 2025). "Mutant IDH1 glioma cells promote the conversion of α-ketoglutarate to (R)-2-hydroxyglutarate (2HG), an inhibitor of α-ketoglutarate-dependent enzymes." (PMID 40964044, 2025). "For example, IDH1-mutant glioma cells were shown to release D-2-hydroxyglutarate (D2HG), which promotes lactate accumulation in peritumoral neurons via the mTOR pathway, thereby increasing neuronal hyperexcitability and seizure risk." (PMID 40718831, 2025). "We generated ectopic mouse tumor xenografts from either glioma or sarcoma cell lines that we modified to stably over-express IDH1 WT, R132H, or R132Q, and performed comprehensive epigenomic and transcriptomic analyses on these tumors." (PMID 40188944, 2025). "To elucidate their molecular impact, we performed proteome analysis on patient-derived (PD) and U87MG glioma cell models with either mutant or wild-type IDH1." (PMID 41009641, 2025). "The therapeutic promise of biomarker-driven therapies in neuro-oncology was highlighted by a phase I clinical trial that found ivosidenib was well tolerated and resulted in sustained disease stabilization in a subset of patients with IDH1-mutant gliomas." (PMID 41311621, 2025). "Following early data showing Ivosidenib Suppressed tumor 2-HG in glioma, Vorasidenib, a dual IDH1/2 inhibitor with improved brain penetrance, was evaluated in a Phase I study (NCT03343197)." (PMID 40931345, 2025). "From receiver‐operating characteristics (ROC) curves, the resulting area under the curve (AUC) values for distinguishing tumor from normal brain tissue and for differentiating the glioma IDH1 genotypes were 0.9992 and 0.9801, respectively." (PMID 40171868, 2025). "Although our algorithm has achieved significant results in glioma grading, IDH1 classification, pituitary tumor classification, it also exhibits certain limitations." (PMID 40127071, 2025). "qPCR analysis of 38 genes was investigated, including the glioma cell marker, GFAP; prognostic glioma classification markers, IDH1/2; and glioma cell stemness markers, NANOG, SOX2, SOX2-OT and CD133." (PMID 41034696, 2025).
glioma (continued). "In gliomas, alterations in the Isocitrate dehydrogenase 1 (IDH1) gene play a pivotal role in tumor formation." (PMID 40520993, 2025). "As an emerging method for detecting unique signals from the molecules of interest, magnetic resonance spectroscopy (MRS) identifies IDH1 mutation by tracking D‐2‐hydroxyglutarate (D‐2HG), an oncometabolite of IDH1‐MUT glioma cells." (PMID 40171868, 2025). "IDH mutations (specifically in IDH1 and IDH2) are genetic alterations that occur in a subset of these tumors, particularly those arising from lower-grade gliomas." (PMID 41294817, 2025). "A total of 66 patients with an established diagnosis of IDH1 mutant glioma (grades 2–4) and progressive disease were enrolled." (PMID 40867259, 2025). "Together, these data suggest that expression of both IDH1 mutants in glioma xenograft models share many transcriptionally down-regulated pathways, though IDH1 R132Q uniquely shows hypermethylation of DNA damage pathways." (PMID 40188944, 2025). "In this study, we introduce a SERS‐based approach coupled with a deep learning model to intraoperatively determine IDH1 status in glioma patients by determining GSH and H2O2 concentrations on freshly excised tumor tissue." (PMID 40171868, 2025). "Neural G0 genes also significantly predicted survival in IDH1/2 mutant gliomas (p val. = 0.006) and show a strong tendency for IDHwt gliomas (p val. = 0.099)." (PMID 40346033, 2025). "Research indicates a strong link between LRP1B deletion and the development of glioma, particularly in patients with wildtype IDH1/2." (PMID 40564017, 2025). "Our findings further support the significance of radiomic features in predicting IDH1 genotype, reinforcing prior research on MRI-based machine learning approaches in glioma classification." (PMID 40299088, 2025). "We observed significantly higher expression in grade 2 and 3 IDH1/2 wt gliomas compared to grade 4 IDH1/2 wt tumors, and also higher expression in IDH1/2 mutant grade 2 and 3 gliomas compared to IDH1/2 wt grade 2 and 3 tumors." (PMID 40346033, 2025). "Among these, we identified 52 potential enzyme inhibitors and selected six for further evaluation, both alone and in combination with TMZ, in glioma cell lines (U87 MG IDH1 WT and mutant) and in GBO-PDC." (PMID 41285884, 2025). "We stratified 798 primary gliomas into 4 molecular subgroups: GBM, IDH1/2-mutant astrocytoma, oligodendroglioma, and other IDH1/2-wild-type gliomas." (PMID 41377022, 2025). "Since 2021, the classification of gliomas has undergone significant changes, with the WHO proposing a new system based on molecular alterations, including IDH1/2 mutation status and 1p/19q co-deletion status." (PMID 40177536, 2025). "IDH1 expression was measured by immunohistochemical methods to analyze the correlation between IDH1 expression in glioma and clinical and ultrasound characteristics." (PMID 40944023, 2025). "For example, mutations in isocitrate dehydrogenase genes (IDH1 and IDH2) are frequently observed in gliomas and acute myeloid leukemia." (PMID 40523311, 2025). "Among them, isocitrate dehydrogenase 1 (IDH1) is one of the most extensively studied molecular markers in glioma." (PMID 40944023, 2025). "In particular, in some cancers with IDH1/IDH2 mutations, such as gliomas, cells become reliant on the de novo pyrimidine synthesis pathway." (PMID 40961924, 2025). "An important molecular diagnosis marker is the genetic mutation in either isocitrate dehydrogenase 1 (IDH1) or isocitrate dehydrogenase 2 (IDH2), which is common in grade 2 and 3 gliomas and defining astrocytoma and oligodendroglioma." (PMID 40564198, 2025).
glioma (continued). "Clinically, IDH1/2-mutant gliomas were associated with lower headache incidence (32.2% versus 50.4% in IDH1/2-wild-type gliomas; P < 0.0001) but higher epilepsy prevalence (36.0% versus 16.9%; P < 0.001)." (PMID 41377022, 2025). "For example, MGMT methylation status influences temozolomide response, and IDH1 inhibitors such as ivosidenib are being investigated in gliomas." (PMID 41311621, 2025). "To increase the likelihood of tumor formation, we used IDH1 WT-, R132H-, or R132Q-expressing glioma (U87MG) and sarcoma (HT1080∗) cells to generate subcutaneous mouse xenografts." (PMID 40188944, 2025). "Overall, Au‐R12P demonstrates potential in intraoperatively identifying IDH1 genotypes of glioma by measuring redox metabolites." (PMID 40171868, 2025). "Glioma-related mutations have been linked to this increased VTE risk – the incidence is strikingly higher in patients with isocitrate dehydrogenase 1 (IDH1) wildtype tumors, which distinguishes glioblastomas from other gliomas." (PMID 39851266, 2025). "IDH (isocitrate dehydrogenase) mutations, predominantly IDH1 and IDH2, are another critical molecular hallmark, commonly associated with lower-grade gliomas and better prognoses." (PMID 40636690, 2025). "The increased ROS further kills the residual IDH1 (R132H) glioma cells, and finally significantly inhibits the recurrence of IDH1 (R132H) glioma." (PMID 40371327, 2025). "A phase 1/2 study investigated olutasidenib (FT-2102), a mutant IDH1 inhibitor, in patients with advanced solid tumors and gliomas, either as monotherapy or combined with azacitidine for glioma treatment." (PMID 40565099, 2025). "Engineered IDH1-mutant glioma cell lines exhibited increased sensitivity to HDACis, including belinostat, and disclosed enhanced apoptotic responses." (PMID 40565099, 2025). "The correlation between Haemophilus and TFAP2C in GBM gains context from evidence linking Haemophilus to IDH1 status and glioma grade." (PMID 41373739, 2025). "Parameters derived from microvascular caliber imaging show strong correlation with histologic findings, indicating that IDH1 mutant gliomas have fewer and less dense micro-vessels." (PMID 40944023, 2025). "This further elucidates the relationship among vascular architecture, IDH1 expression, and glioma grade." (PMID 40944023, 2025). "In our study, wild-type IDH1 gliomas exhibited a more malignant SMI blood flow pattern and pronounced peritumoral edema." (PMID 40944023, 2025). "Inactivating mutations in ATRX have been shown to disrupt immune signaling pathways, such as promoting immunosuppressive mechanisms in IDH1-mutant gliomas and impairing cGAS-STING signaling in sarcomas." (PMID 40495762, 2025). "Here, we provide evidence that RNaseH2 inhibitor candidates can reduce glioma cell survival, particularly in high-grade gliomas with IDH1 wild-type status, a subtype characterized by its aggressiveness and treatment resistance." (PMID 41285884, 2025). "For example, the lncRNA TP53TG1 promotes cell migration and proliferation under glucose-deprived conditions by regulating gene expression of PKM2 and IDH1 in glioma cell cultures." (PMID 40927709, 2025). "As part of a larger international basket trial investigating olutasidenib in solid tumors, this phase 1b/2 study reported outcomes in 26 patients with IDH1-mutant glioma." (PMID 40867259, 2025). "This study demonstrates that machine learning-based radiomic models provide a reliable and noninvasive approach to IDH1 genotype classification in gliomas." (PMID 40299088, 2025). "Precision oncology in CNS cancers is made possible by the molecular pathways covered, including EGFR amplification, IDH1/2 mutations, and MGMT promoter methylation." (PMID 41311621, 2025).
glioma (continued). "A previous study suggests mutant IDH1 has potent antithrombotic activity within gliomas and peripheral circulation." (PMID 38955935, 2024). "IDH1 is reported to regulate podoplanin (PDPN) expression in glioma by regulating its promoter methylation status." (PMID 38241355, 2024). "Both low-grade gliomas and GBM, with wild-type and mutated IDH1, showed correlations with various clinicopathological events, and the difference in ALDOC expression was statistically significant on its own." (PMID 38741139, 2024). "Thus, detecting IDH1 mutations in RGNTs could help further understand these tumors’ pathological features and may be clinically useful in differentiating RGNTs from other gliomas." (PMID 39457636, 2024). "IDH1 mutations are present in over 70% of WHO grade II and III gliomas, as well as in GBM derived from these low-grade lesions." (PMID 39877359, 2024). "Glioma patients with IDH1-mut had a median OS of 21 months compared to 17.5 months for those without an IDH1 mutation." (PMID 38893240, 2024). "Following treatment with Panobinostat, IDH1 mutant glioma cells demonstrated increased cytotoxicity and inhibited proliferation." (PMID 39596840, 2024). "Overall, approximately 80% of adult grade II/III gliomas and secondary glioblastoma multiforme (GBM) harbor mutations at either Arg132 of IDH1 or Arg172 of IDH2, whereas point mutations in the TERT promoter occurred in ~75% of GBM." (PMID 38232086, 2024). "We discovered that rat tumors lack the Idh1 R132 and Idh2 R172 hotspot mutations that are widely implicated in human gliomas (mainly in WHO grade II and III gliomas and secondary glioblastoma)." (PMID 38232086, 2024). "Although many studies and reviews have shown that CDKN2A/B deletion is associated with poor prognosis in diffuse glioma with IDH1/2 mutation, relatively few have reported comprehensively on CNS WHO grade 4 gliomas." (PMID 39457569, 2024). "IDH1 and IDH2 mutations are important, class-defining mutations in gliomas that carry significant therapeutic and prognostic implications." (PMID 39876890, 2024). "IDH1 and IDH2 mutational status is a critical biomarker with diagnostic, prognostic, and treatment implications in glioma." (PMID 38796421, 2024). "We found that treatment with rapamycin also inhibited FASN mRNA and protein expression in IDH1 MT glioma cell lines." (PMID 39149696, 2024). "While IDH1 mutation was the most important factor in identifying patients with the best prognosis, increased 18F-FDG uptake provided additional prognostic information for predicting poor OS in patients with IDH1 wild-type gliomas." (PMID 38932755, 2024). "IDH1-mutant gliomas elevate D-2-hydroxyglutarate (D-2HG) levels, with potential dual effects on tumor progression." (PMID 38982076, 2024). "Hypermethylation, in particular, is associated with mutations in genes like IDH1 and IDH2, which are frequently altered in cancers, such as acute myeloid leukemia, glioma, and chondrosarcomas (CSs)." (PMID 39590345, 2024). "Over 90% of IDH1/2 mutant gliomas harbor the IDH1 p.R132H alteration while IDH1 p.R132C/G/L/S and IDH2 p.R172G/K/M are more rarely observed." (PMID 38796421, 2024). "This is further supported by the better therapeutic effects of TMZ for IDH1-WT glioma patients with MGMT promoter methylation over IDH1-mutants." (PMID 38615034, 2024). "Mutations in the IDH1 and IDH2 genes are common in gliomas, particularly low-grade gliomas and secondary glioblastomas, and are usually associated with specific metabolic abnormalities." (PMID 39457636, 2024). "IDH1 mutations are frequently associated with secondary glioblastomas and confer a better prognosis compared to IDH1 wild-type gliomas." (PMID 39459454, 2024). "We previously reported on a set of compounds that are effective against isocitrate dehydrogenase 1 (IDH1) mutant glioma, including omacetaxine mepesuccinate ((OMA) formerly known as homoharringtonine)." (PMID 39770529, 2024).
glioma (continued). "IDH1 and IDH2 gene mutations and co-deletion of chromosome 1p and 19q are two important diagnostic factors for the prognosis of glioma patients." (PMID 38348047, 2024). "IDH1 mutations are associated with the aberrant conversion of α-KG to D2HG, an oncogenic metabolite that is recurrent in acute myeloid leukemia, glioma, chondrosarcoma, and intrahepatic cholangiocarcinoma." (PMID 38622131, 2024). "A well-recognized oncometabolite is 2-HG, resulting from mutations in the isocitrate dehydrogenase 1 (IDH1) and 2 (IDH2) enzymes in gliomas and acute myeloid leukemia (AML)." (PMID 39684900, 2024). "It is worth noting that the frequency of IDH1 mutations was higher compared to EGFR-amp in Grade 2, 3, and 4 gliomas." (PMID 38893240, 2024). "It is important to keep in mind that the previous classification of central nervous system (CNS) tumors by the WHO in 2016 defined IDH1/IDH2 high-grade gliomas as GBM." (PMID 38891962, 2024). "In agreement with this, lower quantities of glycolytic intermediates, including fructose 1,6-bisphosphate, 3-phosphoglycerate and phosphoenolpyruvate, have been observed in IDH1 mutant glioma tissue." (PMID 39596840, 2024). "Given the pleiotropic effects of VPA, we wanted to understand why IDH1 MT glioma cell lines showed some selectivity to VPA treatment." (PMID 39149696, 2024). "There is strong agreement among various studies that the citric acid cycle is rewired in IDH1 mutant gliomas." (PMID 39596840, 2024). "The most recent World Health Organization criteria have classified adult gliomas into two major categories: Isocitrate dehydrogenase 1 (IDH1) wild type and IDH1-mutant." (PMID 38982076, 2024). "It is worth noting that pyruvate carboxylase expression was elevated in immortalized human astrocytes expressing the IDH1-R132H mutant and in human glioma tissue." (PMID 39596840, 2024). "Another study that developed murine glioma models based on ATRX KO followed by mutant IDH1 overexpression described upregulated pro-inflammatory gene programs and Nfkb1 signaling as characterized by single cell RNAseq and ATAC-seq23." (PMID 38272925, 2024). "Glycolytic flux is reduced in IDH1 mutant glioma tumors compared with IDH1 wildtype tumors as a result of dampened expression of the rate-limiting glycolytic enzymes hexokinase and pyruvate kinase." (PMID 39596840, 2024). "Compared with normal brain tissue, IDH1 mutations, and D-2HG have been identified as driving factors in tumor development and targets for specific therapy in IDH1-mutant glioma models." (PMID 38982076, 2024). "In our study, for instance, we found that only selective inhibition of FASN by TVB-2640 upregulated cholesterol metabolism in IDH1 MT gliomas." (PMID 39149696, 2024). "One of the first advancements was the detection of 1p/19q codeletion in oligodendrogliomas, as well as the finding of mutations in the IDH1 and IDH2 genes in gliomas." (PMID 38807869, 2024). "VPA inhibited the transcription of lipogenic genes and these lipogenic genes showed significant decreases in promoter chromatin accessibility only in the IDH1 MT glioma cell lines tested." (PMID 39149696, 2024). "For instance, IDH1 and IDH2 mutations are frequently found in gliomas and can produce D-2 hydroxyglutarate (D-2HG)." (PMID 38216787, 2024). "IDH1 mutations were found in 82% of gliomas with low TNFRSF19 expression and 38% of gliomas with high TNFRSF19 expression." (PMID 38560169, 2024). "Another phase 1 study evaluated the brain-penetrant IDH1/2 inhibitor vorasidenib in recurrent IDH1/2-mutant gliomas." (PMID 38912846, 2024). "Safusidenib (DS-1001b/AB-218) is an orally available, brain-penetrant, selective inhibitor of R132-mutant IDH1 that has shown efficacy in preclinical models of glioma." (PMID 39876890, 2024).